PRICKLE4 (prickle planar cell polarity protein 4)
Synonyms: C6orf49; OEBT; DKFZp761H221; OBTP
Tractability: No criterion of Open Targets' tractability assessment is met for any kind of drug.
Gene: Protein-coding gene on chromosome 6 (41,780,739 to 41,787,452, forward strand). Ensembl gene ENSG00000278224.
Subcellular location (Human Protein Atlas): Centriolar satellite; Mitotic spindle
Gene Ontology:
Molecular function: protein binding; actin binding; muscle alpha-actinin binding; zinc ion binding
Biological process: actin cytoskeleton organization; heart development; muscle structure development
Cellular component: adherens junction; filamentous actin; nucleus; stress fiber; Z disc
Genetic constraint (gnomAD): Loss-of-function variants: 43 observed, 43.6 expected, observed/expected ratio (o/e) 0.99, 90% interval 0.77 to 1.27. The upper end of that interval is the gene's LOEUF score, 1.27, which puts it in group 5 of 6, group 1 being the genes least tolerant of losing a copy. Missense variants: 526 observed, 504.98 expected, observed/expected ratio (o/e) 1.04, 90% interval 0.97 to 1.12. Synonymous variants: 208 observed, 205.25 expected, observed/expected ratio (o/e) 1.01, 90% interval 0.9 to 1.14.
Homologues: Orthologues: chimpanzee PRICKLE4 (98% identical), macaque PRICKLE4 (92% identical), pig PRICKLE4 (72% identical), rabbit PRICKLE4 (71% identical), dog PRICKLE4 (70% identical), mouse Prickle4 (65% identical), rat Prickle4 (62% identical), guinea pig PRICKLE4 (52% identical), Caenorhabditis elegans alp-1 (20% identical), Drosophila melanogaster Zasp52 (17% identical). Paralogues in human: LDB3 (21% identical), PDLIM5 (21% identical), PDLIM7 (18% identical), PDLIM3 (13% identical), PDLIM4 (13% identical), PDLIM1 (12% identical), PDLIM2 (11% identical).
Diseases named in the same sentence as PRICKLE4 in open-access papers:
PRICKLE4 is named in the same sentence as 8 diseases in open-access papers, as found by Europe PMC text mining. Sharing a sentence is not in itself a finding about the gene and the disease. The quoted sentences say what the papers report.
anencephaly (1 paper, 2018). A rare neural tube defect during pregnancy, resulting in the absence of a large portion of the brain and skull in the fetus. "Five anencephaly cases carried rare or novel CELSR1 missense variants, three of whom carried additional rare potentially damaging PCP variants: 01F377 (CELSR1 c.6362G>A and PRICKLE4 c.730C>G), 2F07 (CELSR1 c.8807C>T and DVL3 c.1622C>T), 618F05 (CELSR1 c.8282C>T and SCRIB c.3979G>A)." (PMID 29205322, 2018).
brain tumors (1 paper, 2026). "Thus, we identified Prickle4 as a key factor that is induced by PARPi and promotes tumor angiogenesis, which underlies the therapeutic resistance against PARPi in IDHmut brain tumors." (PMID 41236163, 2026). "In parallel, nucleic acid‐based approaches such as RNA interference or antisense oligonucleotides could be designed to suppress Prickle4 expression, and advances in lipid nanoparticle delivery may make such strategies increasingly feasible in the brain tumor context." (PMID 41236163, 2026). "Thus, we speculated that increased Prickle4 may promote brain tumor angiogenesis that forms the resistance mechanism to PARPi." (PMID 41236163, 2026).
glioma (1 paper, 2026). A benign or malignant brain and spinal cord tumor that arises from glial cells (astrocytes, oligodendrocytes, ependymal cells). "Collectively, these findings identified the Prickle4‐mediated microenvironmental remodeling as the key resistance mechanism to PARPi, and support the therapeutic promise of multimodal therapy combining PARPi with anti‐angiogenic agents for glioma treatment." (PMID 41236163, 2026). "In principle, a Prickle4‐targeted PROTAC could provide an effective means to deplete Prickle4 protein levels and thereby enhance PARPi efficacy in IDH‐mutant gliomas." (PMID 41236163, 2026).
schizophrenia (1 paper, 2017). A major psychotic disorder characterized by abnormalities in the perception or expression of reality. "These include: VAT‐1, DAD‐1, PAQR9, BCKD, BDH, Prickle4, PP2A, RPL13A, SPRED2, KLP, FAM36A, NAB1, CLSTN3, PEDF‐R, and FZD3 (Frizzled gene previously associated with different psychopathologies, most notably Schizophrenia)." (PMID 27696737, 2017).
tumor (2 papers, 2008 to 2026). "Yet, under veliparib treatment, Prickle4 knockdown further inhibits tumor growth and extends survival." (PMID 41236163, 2026). "Next, we aimed to epistatically identify the necessary role of Prickle4 in mediating tumor angiogenesis and PARPi resistance in the animal model." (PMID 41236163, 2026). "Staining of tumor specimen indicated that treatment of veliparib also induced expression of Prickle4 in GC02 xenografts." (PMID 41236163, 2026). "Together, these results suggest that veliparib‐induced Prickle4 expression in tumor cells may contribute to tumor progression in our model." (PMID 41236163, 2026). "To determine whether Prickle4 induction directly influences endothelial cells or instead functions in an indirect, tumor cell‐derived paracrine manner, we performed immunofluorescent staining for Prickle4, CD31, and GFAP." (PMID 41236163, 2026). "This suggests that veliparib may induce elevated Prickle4 expression in the tumor cells, thereby stimulating pro‐angiogenic factors facilitating tumor vascularization." (PMID 41236163, 2026). "BLI results from these GC02‐IDHmut xenograft tumors on day 28 showed that Prickle4 knockdown did not affect tumor growth, nor did it affect the survival of mice without veliparib treatment." (PMID 41236163, 2026). "Notably, Prickle4 expression did not colocalize with CD31, but was instead associated with the tumor marker GFAP (Pearson's correlation analyses)." (PMID 41236163, 2026).
PRICKLE4 also shares sentences with these, for which no sentence is quoted: breast carcinoma (1 paper); cancer (1); retinal vein occlusion (1).